ENSG00000291242 (novel transcript)
Gene: Long non-coding RNA gene on chromosome 1 (146,472,518 to 146,641,639, forward strand). Ensembl gene ENSG00000291242.
Gene Ontology:
Molecular function: triplet codon-amino acid adaptor activity
Biological process: translation